VCAM1 (vascular cell adhesion molecule 1)
Diseases named in the same sentence as VCAM1 in open-access papers (continued):
Sharing a sentence is not in itself a finding about the gene and the disease.
tumor (continued). "BZM treatment significantly reduced not only Sele, but also Icam1 and Vcam1, expression in the lungs of s.c. xenograft tumor-bearing mice and of E-selectin, ICAM-1, and VCAM-1 protein levels on ECs in vitro." (PMID 35031433, 2022). "Some tumors block T cell homing by reducing the expression of adhesion molecules such as ICAM-1, VCAM-1, and CD34 on the tumor endothelium." (PMID 35211124, 2022). "Neutralization of vascular cell adhesion molecule-1 (VCAM-1) binding significantly inhibited the ability of TAPLT to interact with EC and abrogated the TAPLT-mediated protection of EC against tumor angiogenesis and metastasis." (PMID 35408794, 2022). "Our prior studies showed that integrin α4β1 mediates myeloid cell adhesion to vascular cell adhesion molecule 1 (VCAM-1) on endothelium, leading to tumor inflammation and growth." (PMID 35365657, 2022). "Vascular system dysregulation and inadequate endothelial energy in tumor tissues downregulate the expression level of intercellular adhesion molecule 1(ICAM1) and adhesion molecules VCAM1, which limits T cell infiltration in tumor tissues." (PMID 35935930, 2022). "Changes in tumor EC properties under inflammatory conditions with direct consequences for leukocyte tumor infiltration are altered expression of P- and E-selectin, ICAM-1 and ICAM-2, VCAM-1 and CD31/PECAM-1." (PMID 35216427, 2022). "The excessive activation of VEGF-VEGFR pathways can directly inhibit the trafficking of immune cells to the tumor by inhibiting upregulation of the expression of intercellular adhesion molecule-1(ICAM-1) and vascular cell adhesion molecule-1(VCAM-1)." (PMID 33791214, 2021). "Overproduction of pro-angiogenic factors such as VEGF in tumours can result in a decrease in the expression of adhesion molecules such as ICAM-1 and 2, VCAM-1, and CD34." (PMID 33917287, 2021). "We found that inhibition of VEGF with mcr84 elevated the expression of VCAM-1 and ICAM-1 on tumor endothelium in 4T1 tumors." (PMID 34673569, 2021). "Many surface markers, including CD106 (Vcam1), CD51 (Itgav) and CD61 (Itgb3), are heterogeneously expressed in the mesenchymal YFP+ EpCAM– population of tumor cells in more than 75% of tested tumors." (PMID 34072345, 2021). "Considering that shed SDC-1 increases VCAM-1 expression, shed SDC-1 delivered from distant tumor microenvironments similarly promotes growth in otherwise dormant cancer cells and thus facilitates disease relapse and metastasis." (PMID 35118073, 2021). "Myofibroblasts bind to LBP-lipopolysaccharide complexes to induce expression of HCC tumor expressed MCP1 (log2 fold change = −7.42) and VCAM1 (log2 fold change = −2.46), which displayed increased expression in the HCC tumors in this study." (PMID 33995488, 2021). "In contrast, downregulation of these adhesion molecules (e.g., ICAM-1/2, VCAM-1, MAdCAM-1, E-selectin) on TEC leads to a decreased infiltration of putative tumor-directed lymphocytes into the TME." (PMID 34638420, 2021). "In addition, tumor vascular ECs also downregulates the level of adhesion molecules on cell surface, which limits the trafficking of immune effector cells into tumors, such as vascular cell adhesion molecule-1 (VCAM-1) and intercellular adhesion molecule-1 (ICAM-1)." (PMID 34930293, 2021). "In our dataset, TME-derived TNF appears to interact with HCC tumor cells expressing TNFRSF1B to induce upregulation of HCC-derived CCN2 (log2 fold change = −4.10), MIP2 (log2 fold change = −6.14), and VCAM1 (log2 fold change = −2.46)." (PMID 33995488, 2021). "The downregulation of adhesion molecules, such as vascular cell adhesion molecule 1 (VCAM1) and intercellular adhesion molecule 1 (ICAM1), in the tumour microenvironment can inhibit T cell migration to the tumour site." (PMID 34281259, 2021). "Leucocyte infiltration into the tumor requires interactions with several EC receptors, selectins, ICAM1 and VCAM1." (PMID 34073394, 2021).
tumor (continued). "We identified multiple tumor-immune interactions, for example between CXCR3, CCL5, TNFRSF1B, and VCAM1-expressing malignant T cells and macrophages/fibroblasts positive for CXCL9, CCR1, GRN, and IGTB1, respectively." (PMID 33816243, 2021). "Each tumor cell type is distinguished by the involvement of typical biological factors (e.g., DKK-1, Wnt, and PSA in PC and IL-6 plus VLA-4/VCAM-1 pathway in MM)." (PMID 33224935, 2020). "The recruitment of these myeloid cells is promoted by the release of CCL5 by activated endothelial cells and their expression of the adhesion molecules VCAM-1, VAP-1, and E-selectin, all induced by clots on tumor cells." (PMID 33042789, 2020). "Vascular cell adhesion molecule-1 (VCAM-1) is also found expressed in LSECs, which participates in tumor-stromal interactions." (PMID 33262947, 2020). "In a previous work, we reported the NFkB-induced expression of CXCR7 concomitant to the perturbation of the CXCR4/CXCL12 and VCAM-1/VLA-4 integrin axes, consistent with experimental evidence of its involvement in immune cell recruitment and tumor metastasis." (PMID 33062419, 2020). "Consistently, IHC staining of xenograft tumor tissues using TGF-β, BMP4, ICAM1 and VCAM1 antibodies indicated suppression of the TGF-β signaling pathway status in PGAM1 silencing cancer cells compared to that in the control group." (PMID 32855383, 2020). "Immune cell effectors must receive cues to adhere and extravasate from the vasculature in order to enter the tumor microenvironment and we observed that 2′3′-cGAMP and IFN-β co-operate to upregulate E-selectin, ICAM-1, and VCAM-1." (PMID 33013881, 2020). "In this work, we established a direct correlation between DDR1 phosphorylation and tumor cell expression of ICAM1 and VCAM1." (PMID 32090682, 2020). "Since VCAM-1 is also involved in inflammatory and angiogenic processes, we next determined which part of its expression was attributable to tumor cells (human VCAM-1), or to the inflammatory and endothelial cells (mouse VCAM-1) using RT-qPCR." (PMID 31340603, 2019). "This different adhesion behavior could be due to the fact that with VCAM-1 there is only one single binding possibility for the macrophages, whereas the surface of an endothelial cell offers several binding partners and thus a higher binding affinity between tumor cells and endothelial cells." (PMID 30717801, 2019). "Better bioavailability (13 fold) of succinobucol NPs enhances the inhibition of vascular cell adhesion molecule-1 (VCAM-1) invasion and tumor cell migration." (PMID 31661003, 2019). "Tissue-resident memory T-cells release interferon-γ (INFγ), which led to upregulation of vascular cell adhesion molecule 1 (VCAM-1) on endothelial cells and enhanced recruitment of circulating T-cells to tumours." (PMID 31656546, 2019). "Anti-tumor: IL-12 promotes NKp46+CD49b−RORγt+ILC3 expansion and upregulation of VCAM1 to facilitate immune leukocyte infiltration resulting in tumor suppression." (PMID 32117199, 2019). "Another report indicated that VCAM-1, commonly overexpressed in RCC, was involved in tumor immune evasion." (PMID 31723229, 2019). "Analysis of the results revealed that genetic depletion of Il1b in fibroblasts in the primary tumour led to a significant decrease in the expression of E-Selectin, P-Selectin, ICAM-1 and VCAM-1 and in ECs sorted from primary tumours." (PMID 31558756, 2019). "Thus, targeting VCAM-1 may be an effective strategy for regulating tumor angiogenesis." (PMID 31575085, 2019). "VEGF-A decreases the adhesive interaction between lymphocytes and tumor vascular endothelial cells, and reduces TIL penetration through deregulation of intercellular adhesion molecule-1 (ICAM-1) and vascular cell adhesion-molecule-1 (VCAM-1)." (PMID 30200478, 2018). "Binding of these integrins to their ligands, like VCAM-1 and ICAM-1, present on tumor vasculature leads to a firm arrest of leukocyte motion." (PMID 30386740, 2018).
tumor (continued). "IFN-γ (type II IFN) acts on tumor cells to induce the upregulation of VCAM-1 and MHC-I expression, thereby enhancing the presentation of tumor antigens." (PMID 30115069, 2018). "It is also possible to push CSC differentiation by blocking BMP and EGFR mediated signals, to prevent tumor vascularization by inhibiting VEGF, to increase tumor sensitivity by interfering with niche adhesion molecules (N-Cadherin and VCAM1)." (PMID 30510501, 2018). "Two additional genes (CD14 and CSNK2A1) were dysregulated in MSS tumours and two genes (CARD11 and VCAM1) were downregulated and six genes were upregulated (LYN, TICAM2, ICAM1, IL1B, CCL4 and PTGS2) in MSI tumours." (PMID 29188362, 2018). "To investigate the role of VCAM-1 on tumor formation in vivo, we administered a subcutaneous injection of PANC-1 cells with stable knockdown of VCAM-1 (sh-VCAM-1) or mock cells (sh-NC) into the subcutaneous bilateral hind leg of athymic nude mice." (PMID 29670110, 2018). "The extravasation of T cells into the tumor tissue depends on the expression levels and clustering patterns of intercellular adhesion molecule-1 (ICAM-1) and vascular cell adhesion molecule-1 (VCAM-1)." (PMID 29774034, 2018). "Furthermore, downregulation of VCAM-1 could repress tumor growth in mouse xenograft models." (PMID 29670110, 2018). "VCAM-1 expressed on the surface of tumors interacts with VLA4 on monocytes/macrophages, which promotes tumor invasion, angiogenesis and metastasis." (PMID 30375429, 2018). "The adhesion molecules ICAM-1, VCAM-1, E-selectin and galectin-3 as well as the chemokine system CXCL12/CXCR4 have been reported to be involved in the interaction of tumor and endothelial cells." (PMID 29100413, 2017). "tHSCs are tumor-promoting cells, which express intercellular adhesion molecule 1 (ICAM-1) and vascular cell adhesion molecule 1 (VCAM-1) among other factors to promote cancer cell migration and proliferation." (PMID 28903404, 2017). "IHC staining of mice tumor biopsies revealed increased expression of fibronectin and FAP, and decreased expression of E-cadherin and VCAM-1 after exosomes treatment." (PMID 28178689, 2017). "The immunohistochemical staining for mice tumor biopsies also revealed increased expression of fibronectin and FAP, along with decreased expression of E-cadherin and VCAM-1 after exosomes treatment." (PMID 28178689, 2017). "Endothelial activation markers, including vascular cell adhesion molecule-1 (VCAM-1) and vascular adhesion protein-1 (VAP-1), are induced near metastatic tumor cells after their attachment to the vascular bed." (PMID 28955335, 2017). "It further increased T cell homing into tumor tissues after an adoptive transfer which was inhibited by anti-ICAM-1 and anti-VCAM-1 blocking antibodies." (PMID 28665313, 2017). "Using MRM‐based quantification, it was found that VCAM1, CALB1, CSPG4, and VTDB also dynamically changed with tumor progression." (PMID 28980450, 2017). "The administration of the NGR-TNF protein results in VCAM-1 and ICAM-2 upregulation on the tumor endothelium, favoring T cell trafficking." (PMID 28665313, 2017). "The cell-cell adhesion leads to clustering of VCAM-1 and the cytoplasmic domain of this clustered VCAM-1 particularly activates Ezrin which in turn activates the PI3K/AKT signaling that suppresses apoptosis and promotes survival signal in the tumour cells." (PMID 26881177, 2016). "The effects of selenoglycoproteins and tumor cell infusion on the expression of selected cell adhesion molecules, namely ICAM-1, VCAM-1, and ALCAM, were evaluated by quantitative reverse transcription PCR." (PMID 26706037, 2016). "A B-cell associated signature distinguished HPV(+) from HPV(−) tumors, and included the DEGs CD200, GGA2, ADAM28, STAG3, SPIB, VCAM1, BCL2 and ICOSLG; the immune signal relative to T-cells was qualitatively similar between TILs of both tumor cohorts." (PMID 27462861, 2016).
tumor (continued). "Expression of adhesion molecules, including ICAM-1, VCAM-1, and endothelial leukocyte adhesion molecule-1 (ELAM-1), on endothelial cells is critical for tumor cell invasion and metastases." (PMID 26823953, 2016). "These cytokines induce tumor cells to increase expression of some proinflammatory molecules such as P-selection, CXCR4, I-CAM1 and VCAM-1 adhesion molecules." (PMID 24583847, 2014). "Egfl7 can promote tumor growth by repressing ICAM-1 and VCAM-1 expression, then limiting immune cell infiltration, as observed in breast and lung carcinoma murine models." (PMID 24734218, 2014). "Among downregulated proteins, PTEN is a well known tumour suppressor in CRC, while CDC20, TNF and VCAM1 are important protooncogenes." (PMID 25594007, 2014). "ATP or UTP was able to induce ICAM-1 and VCAM-1 expression at very low doses (100 nM) via P2Y2R activation, which indicates that ATP levels within the tumor microenvironment are sufficient to stimulate P2Y2R in MDA-MB-231 or ECs." (PMID 25156554, 2014). "The accumulation of CIK cells was increased around the tumor vessels with high expressions of ICAM-1 and VCAM-1, indicating that CIK cells infiltration is related with endothelial cell adhesion molecules." (PMID 23799045, 2013). "We found that the accumulation of tumor infiltrating CIK cells was correlated with the expression of ICAM-1 and VCAM-1." (PMID 23799045, 2013). "Tumor cell integrins are able to bind to various secreted proteins on ECM, or receptors such as vascular cell adhesion protein 1 (VCAM1) expressed on stroma, which induce quiescence, modulate pro- and anti-apoptotic molecules, and consequently lead to CAM-DR." (PMID 22746994, 2012). "We cultured CLL cells together with the murine BM-derived cell line M2-10B4, a commonly used model system for tumor cell-marrow interactions, Expression of the VLA-4 ligand, VCAM-1, on the surface of M2-10B4 cells was confirmed by flow cytometry." (PMID 21876768, 2011). "On the opposite, EphB4, FGFR1, Tie2, Alk5, TNFR2, and the adhesion molecules VCAM-1 and ICAM-1 were more frequently detected and at higher levels in normal kidney endothelium as compared to tumor endothelium from intermediate and large tumors." (PMID 22235379, 2011). "Metronomic gemcitabine also significantly increased apoptosis in cancer-associated fibroblasts and induced greater reductions in the tumour levels of multiple pro-angiogenic factors, including EGF, IL-1α, IL-8, ICAM-1, and VCAM-1." (PMID 20531411, 2010). "LTA induces the expression of vascular cell-adhesion molecule 1 (VCAM1) on vascular endothelial cells and recruits natural killer (NK) cells to parenchymal organs and tumor lesions." (PMID 18700950, 2008). "In several tumour cell lines, TNF-α induced the expression of several different adhesive molecules including several integrin subunits, ICAM-1 and VCAM-1." (PMID 15841081, 2005). "This was again opposite to that PAK4KO promoted ICAM-1 and VCAM-1 expression and vascular normalisation in a syngeneic mouse model, suggesting the PAK4KO-stimulated anti-tumour immunity may contribute to its effect on vascular normalisation." (PMID 41228228, 2025). "Moreover, RT upregulates adhesion molecules like intracellular adhesion molecule 1 (ICAM-1) and vascular cell adhesion molecule 1 (VCAM-1) on tumor blood vessels, facilitating CAR-T cell infiltration into the tumor microenvironment." (PMID 39881333, 2025). "Additionally, adhesion molecules such as VCAM-1 and ICAM-1 contribute to metastatic progression by mediating tumor–bone interactions." (PMID 41183210, 2025). "Others have shown that vascular cell adhesion molecule 1 (VCAM-1), facilitating trans-endothelial migration is expressed on both endothelium and tumour cells allowing interaction with very late antigen-4 (VLA-4) antigens on leukocytes to activate PI3K pathway for tumour progression." (PMID 39792888, 2025).
tumor (continued). "Vascular remodeling normalizes tumor vessels, enhancing adhesion molecule expression like intercellular adhesion molecule 1 (ICAM-1) and vascular cell adhesion molecule 1 (VCAM-1), facilitating immune cell entry and forming high endothelial venules for immune priming." (PMID 41373749, 2025). "Tumor blood vessels often lack proper endothelial junctions and adhesion molecules, such as intercellular adhesion molecule-1 (ICAM-1) and vascular cell adhesion molecule-1 (VCAM-1), which are essential for T cell extravasation." (PMID 41048631, 2025). "However, unlike in BALB/c mice that saw a reduction in lung metastasis, the lung metastatic signal, normalized to primary tumor volume, was increased in NSG mice bearing Vcam1-KO tumors." (PMID 40955669, 2025). "However, the localised expression of VCAM-1 in extracolonic sites of carcinogenesis and inflammation raises the possibility of identifying and treating IBD comorbidities and secondary tumours of metastatic CRC." (PMID 40095109, 2025). "Experimental studies in H22 tumor-bearing models and orthotopic HCC models revealed that this nanosystem leverages enhanced glypican-3 (GPC3) and tumor vascular cell adhesion molecule-1 (VCAM1) targeting to recognize and capture CTCs." (PMID 40528159, 2025). "Moreover, STING signaling enhances the expression of adhesion molecules such as E-selectin, vascular cell adhesion molecule-1 (VCAM-1), and intercellular adhesion molecule-1 (ICAM-1) on tumor endothelial cells, thereby facilitating T cell extravasation." (PMID 41204180, 2025). "In tumor samples, CXCL-12, VCAM-1, and ICAM-1 levels negatively correlated with surgery duration." (PMID 40652770, 2025). "Mechanistically, FGFR blockade suppresses CAF proliferation and migration, as well as the release of vascular cell adhesion molecule 1 (VCAM-1) via MAPK/ERK pathway downregulation in CAFs, disrupting both physical and chemical barriers in the tumor immune microenvironment (TIME)." (PMID 40813760, 2025). "Additionally, FIRRE has been shown to regulate the expression of immunomodulatory genes, such as VCAM1 and TNF-α, indicating its role in modulating the tumor immune microenvironment." (PMID 39981249, 2025). "In the Oncology VascHT29 Combo ELECT system, Keytruda (50,000 ng/mL) also reversed the hsa/mtCXCL8-mediated inhibition of key adhesion molecules like VCAM-1, CXCL-10, CXCL-9, and CD69 at the highest dose, promoting immune cell adhesion and recruitment into the tumor site." (PMID 40124384, 2025). "Notably, tumor cell membranes also highly express CD44 receptors, integrin receptors, ICAM-1, and VCAM-1." (PMID 40528159, 2025). "Metastatic progression further relies on NF-κB-mediated induction of cell adhesion molecules, such as vascular cell adhesion molecule-1 (VCAM-1), endothelial leukocyte adhesion molecule (ELAM-1), and ICAM-1, which facilitate the tumor cell‒endothelial interactions critical for extravasation." (PMID 40562870, 2025). "Not only surface VCAM-1, but also secreted VCAM-1 seems to promote tumor progression." (PMID 40071851, 2025). "Additionally, RT can normalise tumour blood vessels by increasing the expression of adhesion molecules ICAM-1 and VCAM-1, which facilitates CAR-T-cell migration into the tumour." (PMID 40906384, 2025). "Furthermore, the dual-targeting strategy utilizing anti-VCAM1 mAbs and anti-GPC3 mAbs enhances the specificity and sensitivity of therapy toward both CTCs and primary tumor cells, thereby improving overall therapeutic outcomes." (PMID 40528159, 2025). "Tumor cells often promote angiogenesis by producing vascular endothelial growth factor (VEGF), which typically reduces the expression of vascular cell adhesion protein 1 (VCAM-1), thereby hindering T cell migration into the TME." (PMID 38545114, 2024).